FOXP3 (forkhead box P3)
Diseases named in the same sentence as FOXP3 in open-access papers (continued):
Sharing a sentence is not in itself a finding about the gene and the disease.
breast carcinoma (continued). "Previous studies have reported that the prognostic value of FOXP3+ TILs in breast cancer is worse because of their immunosuppressive function." (PMID 35565267, 2022). "As downstream targets of FOXP3, miR-200c and miR-141 were downregulated in the breast cancer tissue of animal models and TCGA human breast cancer tissue samples but upregulated in plasma samples of both humans and mice with metastatic disease." (PMID 36012638, 2022). "In this study, we demonstrate that high frequencies of CD163+ and FoxP3+ cells in the tumors of patients with breast cancer co-exist with CD8+ cells only when the latter are also in dense frequencies." (PMID 36551693, 2022). "In 2017, an elegant paper was published focusing on FoxP3-inducible breast cancer cells and Foxp3 heterozygous Scurfy mutant (Foxp3 sf/+) female mice to identify a FOXP3-KAT2B-miR-200c/141 axis." (PMID 35565446, 2022). "A meta-analysis showed that tumor-infiltrating Foxp3+ regulatory T cells in patients with breast cancer predicted poor recurrence-free survival." (PMID 35047040, 2022). "Compared with normal tissues, FOXP3 is highly expressed in a variety of tumors, including stomach cancer, esophageal cancer, and breast cancer and so on." (PMID 36550816, 2022). "The database analysis and IHC in this study testified that the expression levels of FOXP3 in human breast cancer were higher than in normal tissues, and its expression levels were not related to the tumor stage, histological type and race." (PMID 35614183, 2022). "A significant correlation has been reported between CTLA-4 and FoxP3 expression in PBMCs of patients with breast cancer." (PMID 36146549, 2022). "The survival analysis found that high transcription levels of FOXP3 in breast cancer patients resulted in worse PPS and had better PFS." (PMID 35614183, 2022). "In the SweBCG91RT trial, immune infiltrates, in the form of CD8+ T cells and FOXP3+ T cells, were examined in early-stage breast cancer patients that received breast-conserving surgery (BCS) and postoperative radiotherapy." (PMID 36387071, 2022). "For example, FOXP1 protein overexpression is associated with poor prognosis in several hematological diseases, while serving as a tumor suppressor in breast cancers; FOXP3 also indicates a better prognosis for breast cancers." (PMID 36148946, 2022). "A high ratio of CD8+ or CD3+ on FOXP3 T cells has already been described as being correlated with a good prognosis in human colon cancer patients and in breast cancer." (PMID 35339889, 2022). "In this report, we have shown a direct correlation between densities of CD8+ cells with densities of CD163+ and FoxP3+ cells in the primary tumors of patients with breast cancer." (PMID 36551693, 2022). "S100A8+ ICs were already present in early stage of breast cancer and were associated with increased CD4+, CD8+, FOXP3+ TILs and PD-L + ICs infiltration." (PMID 33146829, 2021). "We found that CD177+ or CD177− TI Treg cells, defined as CD4+CD25+CD127low, from human cancer specimens exhibited a similar level of FOXP3 protein in 1 breast cancer, 2 colon cancers and 3 ccRCCs." (PMID 34599187, 2021). "While the exact functions of CXCL10 on FOXP3+ Tregs in breast cancer remain yet to be elucidated, it can be concluded that CXCL10 expression is associated with FOXP3+TIL infiltration in both DCIS and invasive carcinoma." (PMID 34504204, 2021). "In breast cancer, FOXP3 can perform its anticancer function by regulating the expression of tumour-related genes." (PMID 34307133, 2021). "In breast cancer, it was found that FOXP3 and miR-155 work together to down regulate ZEB2, resulting in reduced invasion." (PMID 33800594, 2021). "FOXP3 downregulated the expression of MTA1 in breast cancer cells by directly inhibiting MTA1 promoter activity." (PMID 34307133, 2021).
breast carcinoma (continued). "FOXP3, as a tumour suppressor molecule in breast cancer, plays a variety of tumour suppressor roles by regulating the transcriptional levels of a series of tumour-related genes." (PMID 34307133, 2021). "Human and murine breast cancer growth and metastasis require regulatory immune cells, such as regulatory T cells (FoxP3+Tregs), B cells (Bregs), and myeloid-derived suppressor cells (MDSCs) to inhibit antitumor immune cells." (PMID 34707136, 2021). "Combined with the results of previous in vitro and in vivo experiments, these results demonstrated that FOXP3 can hinder breast cancer metastasis by downregulating MTA1 expression." (PMID 34307133, 2021). "This pattern suggests that FOXP3 regulates the expression of downstream molecules in addition to MTA1 to inhibit breast cancer metastasis." (PMID 34307133, 2021). "CD8‐positive cytotoxic T cells and FOXP3‐positive regulatory T cells are key players in antitumor immunity that positively and negatively correlate with the prognosis of breast cancer patients, respectively." (PMID 33506656, 2021). "Thirdly, the FOXP3-miR-146-NF-κB as an oncotarget and its axis has a functional role during tumor initiation in both prostate and breast cancers." (PMID 34768829, 2021). "We transfected the pcDNA3.1(-)-FOXP3 plasmid into MCF-7 breast cancer cells and determined the mRNA expression levels of the 7 selected potential downstream molecules of FOXP3 through real-time PCR." (PMID 34307133, 2021). "There is also evidence showing that FOXP3 suppresses angiogenesis by inhibiting VEGF expression in breast cancer, and on T regulatory cells, FOXP3 contributes to immunosuppression in a NRP1-dependent manner." (PMID 34249735, 2021). "CD177+ or CD177− TI Treg cells had similar expression of FOXP3 mRNA in 5 breast cancers based on a published RNAseq dataset (GSE89225)." (PMID 34599187, 2021). "The previous study demonstrated the inverse correlation between breast cancer angiogenesis and nuclear FOXP3 expression." (PMID 34938323, 2021). "The results showed that the expression level of FOXP3 in the nucleus was negatively correlated with lymph node metastasis from breast cancer and pathological stage, while the expression level of MTA1 was positively correlated with these parameters." (PMID 34307133, 2021). "More recently, two analyses of RNAseq of TI Treg cells reported the use of the ratios CCR8/FOXP3 for breast cancer and CCR8/CD3G for lung and colorectal cancers, which had a modest predictive value in terms of overall survival." (PMID 34599187, 2021). "Immunohistochemistry (IHC) for CD8 + and FOXP3 + was performed in 87 formalin-fixed paraffin-embedded primary breast cancer tissues, and cell infiltrate was assessed under light microscope." (PMID 34117905, 2021). "Analysis of tumor tissue from 50 postpartum and 7 np breast cancer patients, grouped by reproductive categories.IHC of IL-10 and FoxP3." (PMID 33649008, 2021). "We analysed the correlations between lymph node metastasis from breast cancer, pathological stage and the expression levels of FOXP3 and MTA1." (PMID 34307133, 2021). "Statistical analysis of the protein expression pattern of FOXP3 with the clinicopathological variables of patients with breast cancer." (PMID 34938323, 2021). "Correlation study of FOXP3 mRNA expression with clinicopathological parameters in North Indian breast cancer patients." (PMID 34938323, 2021). "Study of breast cancer suggested that FOXP3 function as a key tumor suppressor through the up-regulation of CXCR4 and down-regulation of CXCL12, which thereby stimulate cell migration." (PMID 33869044, 2021). "In mammary cancers, FOXP3 is found to regulate HER-2 and SKP2 by repressing their expression, and importantly these genes are linked to a poor prognosis in the cases with breast carcinoma." (PMID 34938323, 2021).
breast carcinoma (continued). "FOXP3, as a tumour suppressor gene, has a vital function in inhibiting the metastasis of breast cancer cells, but the mechanisms by which it inhibits metastasis have not been fully elucidated." (PMID 34307133, 2021). "Our study provides not only further knowledge about the mechanism by which FOXP3 inhibits breast cancer metastasis but also an experimental basis and new ideas for the treatment of metastatic breast cancer." (PMID 34307133, 2021). "Correlation study between FOXP3 protein expression and its promoter methylation in patients with breast cancer." (PMID 34938323, 2021). "Due to these captivating characteristics of FOXP3, the present work examines the correlation of FOXP3 protein expression with the clinicopathological variables to strengthen its role as a putative biomarker for breast carcinoma in the Indian population." (PMID 34938323, 2021). "Conversely, FOXP3+ regulatory T cells assessed in treatment naïve tumors were shown to be an indicator of poor prognosis in HR+ breast cancer, but of favorable prognosis in HR-/HER2+ tumors." (PMID 34135901, 2021). "We systematically explored a new mechanism by which FOXP3 inhibits breast cancer metastasis via the FOXP3-MTA1 pathway." (PMID 34307133, 2021). "Concordantly, some studies have revealed that blocking of STAT3 in breast cancer animals significantly decreased the Tregs proportion in the TME especially the Foxp3+ Tregs." (PMID 33957948, 2021). "In breast cancer, FOXP3 can regulate the expression of tumour-related genes to perform its anticancer function." (PMID 34307133, 2021). "Analysis of 1166 breast cancer patients in The Cancer Genome Atlas (TCGA) database and breast cancer case data in GEPIA showed that the FOXP3 expression level was negatively correlated with the MTA1 expression level, consistent with our results." (PMID 34307133, 2021). "The finding depicts a strong association between promoter hyper-methylation and mRNA expression in deactivating or down-regulating the possible role of FOXP3 in the suppression of breast cancer." (PMID 34938323, 2021). "Interrogation of a TCGA cohort of breast cancer patients identified a positive correlation between levels of FOXP3 and miR-200 members in breast cancer samples, and reduced expression of miR-200 in tumors from patients with metastatic disease." (PMID 34884985, 2021). "The study has also pointed out the high expression of FOXP3 as a good predictor of the survival of a patient in prostate cancer, breast cancer, gastric cancer, and bladder cancer." (PMID 34938323, 2021). "In recent years, a large number of studies have shown that FOXP3 is also a tumour suppressor gene in breast cancer." (PMID 34307133, 2021). "Similar observations were made in breast cancer patients treated with NACT where a high CD8+/FOXP3+ ratio in residual tumors was prognostic." (PMID 32852603, 2021). "Our experiment revealed that MTA1 is a new target gene of FOXP3 that regulates breast cancer metastasis and provides further knowledge about the mechanism of FOXP3 in breast cancer metastasis." (PMID 34307133, 2021). "Using dual-color IHC staining, we identified CD177- and FOXP3-double-positive cells in breast cancer sections (red arrow)." (PMID 34599187, 2021). "Specifically, elevated Foxp3 gene expression and accumulated Foxp3+ Tregs amount were detected in close proximity to lung metastases of breast cancer, as well as higher STAT3 activities." (PMID 33957948, 2021). "Two other strategies to suppress TME Tregs in patients with breast cancer are anti-FoxP3 anti-CD25 treatment." (PMID 32937885, 2020). "Immunohistochemistry was used to detect tumour-infiltrating CD20+ (B), CD4+ (helper T), CD8+ (cytotoxic T) and FoxP3+ (regulatory T) cells in breast cancers from 62 patients, with quantification in tumour stroma, tumour cell nests, and tumour margins." (PMID 32577938, 2020). "In contrast, other studies have shown that tumor FOXP3 expression is a favorable prognostic factor for breast cancer." (PMID 32884895, 2020).
breast carcinoma (continued). "CD4+ CD25+ FoxP3+ Treg cells are a major immunosuppressive cell and, while they prevent deleterious autoimmune diseases, their presence in the breast cancer TME are a significant hurdle for effective BC vaccine responses." (PMID 32937885, 2020). "Preliminary support is available from demonstrations that FAP-positive S1 breast cancer fibroblasts promote the formation of FoxP3-positive T cells in a manner involving B7H3, CD73 and DPP4." (PMID 33153037, 2020). "We evaluated the immunohistochemical expression of PD-L1 and FOXP3, and the extent of tumour infiltrating lymphocytes (TILs) in a large cohort of metaplastic breast cancers, with survival data." (PMID 32939056, 2020). "For example, removal of the DBC1 gene in a breast cancer mouse model increased resistance to experimental autoimmune manifestations by attenuating FOXP3 degradation." (PMID 32316975, 2020). "This study examined the impact of depleting Foxp3+ regulatory T cells (Treg), on lung metastases, using a mouse model of breast cancer." (PMID 32447412, 2020). "In reviewing the literature, we found that the CD8/Foxp3 ratio had a positive effect on prognosis in a number of tumours, including osteosarcoma, colorectal cancer and breast cancer." (PMID 32758195, 2020). "Of note, we observed an association of the CD80/FOXP3 mRNA ratio with poor OS and DFS in breast cancer patients." (PMID 32601304, 2020). "A more recent study showed that loss of FoxP3 expression by human Tregs mediated by TNF-α depends on the FoxP3 complex component Deleted in Breast Cancer 1 (DBC1)." (PMID 33384654, 2020). "FoxP3+ Treg cells and invasive breast cancer cells secrete matrix metalloproteinases (MMPs) and vascular endothelial growth factors (VEGFs) to degrade the ECM and promote angiogenesis, resulting in breast cancer metastasis." (PMID 33234169, 2020). "On the one hand, FOXP3 can act as a tumor suppressor in breast cancer, ovarian cancer, colon cancer, and gastric cancer, but it can act as an oncogene in non-small cell lung cancer, lung adenocarcinoma, and thyroid cancer." (PMID 32793281, 2020). "It is reported that lactic acid can induce large percentage of Foxp3+ Treg cells in breast cancer by plasmacytoid dendritic cells and induce NF-kB-mediated Foxp3 activation, hence driving the differentiation of Treg cells from naive CD4+ T cells." (PMID 32180770, 2020). "The dynamics and significance of FOXP3+ TILs in breast cancer after PST remain to be further investigated." (PMID 32401825, 2020). "In this study, the heterozygous Foxp3 sf/+ breast cancer mouse model was used to analyze the regulation of mouse miR-200s during tumor progression." (PMID 31590453, 2019). "CCL20 and FOXP3+ TILs mRNA expression in tumor tissue demonstrated a high correlation (rs = 0.359, P < .001) in this cohort of breast cancer patients." (PMID 31852159, 2019). "We analyzed this correlation by evaluating TILs and FOXP3 in breast cancer tissues to uncover the immune response in breast cancer tumor microenvironment." (PMID 30814616, 2019). "We further evaluated the effects of FOXP3 expression on survival outcomes in breast cancer patients under different lymph node metastasis status." (PMID 31852159, 2019). "Kaplan–Meier survival analysis showed that FOXP3 expression in tumors was strongly correlated with the OS of all breast cancer patients." (PMID 31852159, 2019). "Unlike the blockade of PD-L1, anti-PD-1 alone did not further upregulate TIM-3 and LAG-3 co-expression on CD4+CD25+FoxP3+Helios+ Tregs in the presence of breast cancer cells." (PMID 31614877, 2019). "Other studies have found miRNAs that influence metastasis and cell invasion in breast cancer with their activity being induced by FOXP3 and KAT2B." (PMID 31590453, 2019).
breast carcinoma (continued). "For example, 6 months of letrozole alone or in combination with metronomic cyclophosphamide was able to reduce the presence of intra-tumoral FOXP3+ Tregs in 83 elderly breast cancer patients." (PMID 31533777, 2019). "Some studies have shown that patients with high levels of FOXP3+ TILs have poor chemosensitivity and worse prognosis, while others reported that breast cancer patients with high levels of FOXP3+ T cells had better outcomes." (PMID 30999966, 2019). "We also explored the impact of lactate on the ability of pDCs to induce Tregs and implicated lactate-induced modulation of tryptophan metabolism in pDCs in the expansion of CD4+ FoxP3+ Tregs in breast cancer." (PMID 31440253, 2019). "We found that the co-expression of TIM-3/LAG-3 was upregulated in FoxP3+Helios+ Tregs in the presence of breast cancer cells." (PMID 31614877, 2019). "Conversely, FOXP3 has been reported to be an important tumour suppressor gene in breast cancer, gastric adenocarcinoma, prostate cancer, and non-small cell lung cancer." (PMID 31381571, 2019). "FOXP3 promotes the immune evasion as Treg cell marker suppressing immune response against cancer, while FOXP3 at the Xp11.23 revealed good prognosis in breast cancers as a tumor suppressor by regulating HER-2/ErbB2 or SKP2 oncogene." (PMID 31815635, 2019). "Rats treated with TAM + JEKHT exhibited significantly lower levels of Foxp3 mRNA in mammary tumors than TAM only or JEKHT only groups, which is indicative of a lower level of immunosuppression." (PMID 30640711, 2019). "Expression of FOXP3 and miR-155 are normally high in healthy breast epithelia, but during breast cancer progression FOXP3 is either aberrantly localised to the cytoplasm or is lost." (PMID 29963231, 2018). "Consistent with this, the level of nuclear Gal-1 was significantly higher in nuclear FOXP3-positive breast cancer tissues, compared with adjacent normal tissues in the 53 paired samples." (PMID 29549328, 2018). "As shown in representative images (nuclear FOXP3 expressed in both breast cancer tissue and adjacent normal sample), the abundance of nuclear Gal-1 was higher in primary breast cancer tissue than in adjacent normal tissues." (PMID 29549328, 2018). "Our results not only uncovered a novel regulator of VEGF in breast cancer but also provided novel insight into the breast cancer-suppressing function of FOXP3." (PMID 29970908, 2018). "Taken together, our data uncovered the important role of FOXP3 and its mechanism in the inhibition of breast cancer angiogenesis." (PMID 29970908, 2018). "In the present study, by analyzing the effect of FOXP3 on breast cancer prognosis in the Kaplan–Meier plotter website, we found that FOXP3 is a protective factor for breast cancer survival, which is consistent with previous reports." (PMID 29970908, 2018). "Collectively, these results suggest that FOXP3 plays a suppressive role in breast cancer angiogenesis." (PMID 29970908, 2018). "Here, we demonstrate the presence of the full-length FOXP3 transcript in some breast-cancer tissues." (PMID 29549328, 2018). "The effect of Foxp3 on regulation of the CD44 promoter activity in breast cancer cells was assessed by ChIP and EMSA analysis." (PMID 29747682, 2018). "To assess the expression of FOXP3 in breast cancer cells, we analyzed single-cell RNA-sequencing data on primary breast cancer cells (GSE75688)." (PMID 29549328, 2018). "Nuclear FOXP3 expression was inversely correlated with VEGF expression in clinical breast cancer tissues, and FOXP3 downregulation and VEGF upregulation were both correlated with reduced survival in breast cancer data sets in the Kaplan–Meier plotter." (PMID 29970908, 2018). "Herein, we find that the overexpression of FOXP3 in human MCF7 breast cancer cells increases the level of UBC9 mRNA." (PMID 30011797, 2018).